LRRK2 (leucine rich repeat kinase 2)
Diseases named in the same sentence as LRRK2 in open-access papers (continued):
Sharing a sentence is not in itself a finding about the gene and the disease.
colorectal cancer (7 papers, 2021 to 2025). A primary or metastatic malignant neoplasm that affects the colon or rectum. "Numerous studies have indicated that patients with Parkinson’s disease (PD) who carry the LRRK2 G2019S mutation face elevated risks of developing cancers, including colorectal cancer." (PMID 38607004, 2024). "Some studies have indicated that PD patients with LRRK2 gene mutations have a higher risk of developing colorectal cancer, which contradicts research that does not take PD subtypes into account." (PMID 39563740, 2024). "Moreover, LRRK2 germline mutations are also linked with an overall increased risk of cancer, especially hormone‐related cancers and colorectal cancer." (PMID 36051080, 2022). "Thus, our experimental findings unequivocally underscore the pro-tumorigenic implications of LRRK2 G2019S in the colorectal cancer pathogenesis." (PMID 38607004, 2024). "Therefore, we hypothesized that LRRK2 G2019S promotes the development of colorectal cancer by fostering intestinal inflammation." (PMID 38607004, 2024). "MicroRNAs and small-molecule inhibitors of DCLK1, LRRK2-IN-1, and DCLK1-IN-1 show promise against colorectal and pancreatic cancer cells in vitro, and DCLK1-targeting CAR-T cell (chimeric antigen receptor T cell) immunotherapy reduces tumor growth in murine models of colorectal cancer." (PMID 37863104, 2024).
Onset (7 papers, 2011 to 2022). The age group in which disease manifestations appear. "Most cases of PD are sporadic with aging as the principal risk factor for developing the disease, but mutations of specific genes, e.g., α-synuclein and leucine rich repeat kinase 2 (LRRK2), occur in around 5 % of PD patients causing early- or late-onset PD." (PMID 36358985, 2022). "Together, this suggests that LRRK2 signaling pathways may be central to the processes underlying both LRRK2 familial and sporadic late onset PD." (PMID 28860483, 2017). "PARK2, PARK7, and PINK1 are known to cause early-onset PD with a recessive inheritance mode, while SNCA and LRRK2 are known to cause dominantly inherited PD." (PMID 30917570, 2019). "In early-onset PD, mutations in six specific genes (SNCA, PRKN, PINK1, DJ1, LRRK2, and GBA) have been reported to account for 16% of cases; these specific mutations are not directly accounted for in our estimate, which is based on a polygenic model." (PMID 21738487, 2011).
proteinopathy (7 papers, 2013 to 2025). "First, PD patients carrying LRRK2 mutations present a varying degree of neuropathologies, despite a similar clinical presentation, suggesting a role for LRRK2 in proteinopathy." (PMID 36085537, 2023). "We conclude that the observed neuroprotective effects of PF-475 are due to direct inhibition of LRRK2 activity and that the LRRK2 protein is upstream of the molecular cascade of apoptosis and proteinopathy." (PMID 40363838, 2025). "The links between vesicle metabolism, lysosomes, autophagy and protein misfolding diseases provide a plausible connection between the cellular phenotype observed in this study, and the pathogenesis and pathology of LRRK2 PD." (PMID 24211199, 2013).
pulmonary fibrosis (7 papers, 2022 to 2025). Chronic progressive interstitial lung disorder characterized by the replacement of the lung tissue by connective tissue, leading to progressive dyspnea, respiratory failure, or right heart failure. "LRRK2 inhibition also blocks exocytosis of endo-lysosome–related organelles in type II pneumocytes of the lung that secrete pulmonary surfactant; prolonged inhibition of this process causes pulmonary fibrosis, a side effect that is carefully monitored in ongoing LRRK2 inhibitor clinical trials." (PMID 41406219, 2025). "For instance, a study has shown that leucine-rich repeat kinase 2 (LRRK2) is conducive to alleviate pulmonary fibrosis via preventing alveolar type II epithelial dysfunction and regulating the innate immune responses." (PMID 36211385, 2022). "In a mouse model of pulmonary fibrosis, Leucine-Rich Repeat Kinase 2 (LRRK2) expression is significantly reduced in alveolar type II epithelial (ATII) cells, and LRRK2-deficient ATII cells exhibit an enhanced ability to recruit profibrotic macrophages via the CCL2/CCR2 axis." (PMID 39850880, 2024). "Several of these genes (PELI1, MAP3K8, LAMA3, EMP2, CTNNAL1, CAV1, LRRK2, SFRP4) may also be involved in lung fibrosis, a severe complication of COVID-19." (PMID 37561814, 2023). "However, due to the tissue-specific expression of LRRK2, inhibitors targeting LRRK2 may not always be protective; for example, the reduction of LRRK2 levels could lead to pulmonary fibrosis." (PMID 40406043, 2025).
skin cancer (7 papers, 2010 to 2025). "A possible association between LRRK2 variants and non-skin cancers has also been reported, though the mechanisms of the link remains incompletely understood." (PMID 39175765, 2024). "It was concluded that being a LRRK2 mutation carriers included an increased risk of non-skin cancer compared with sporadic PD subjects." (PMID 33584195, 2021). "The LRRK2 mutation carriers had increased risk of non-skin cancer compared with sporadic PD subjects (OR 2.09; 95% CI 1.16–3.77; p = 0.015)." (PMID 33584195, 2021). "There was a significant association between harboring a LRRK2 mutation all non‐skin cancers combined (OR 2.09; 95% CI 1.16–3.77; p = .015)." (PMID 29568677, 2018). "LRRK2 mutation carriers have significantly increased age and sex adjusted risk of non‐skin cancer compared with iPD subjects (OR 2.09; 95% CI 1.16–3.77; p = .015)." (PMID 29568677, 2018). "LRRK2 mutation carriers have increased risk of non‐skin cancer compared with iPD subjects (OR 2.09; 95% CI 1.16–3.77; p = .015)." (PMID 29568677, 2018). "In light of this, the increased risk of non‐skin cancers in LRRK2 mutation carriers compared with iPD subjects may therefore not come as a surprise." (PMID 29568677, 2018). "The mean age at non‐skin cancer was younger in the LRRK2 subjects (60.5 years) than the iPD subjects (66.3 years)." (PMID 29568677, 2018). "The proportion of non‐skin cancers was slightly higher in the LRRK2 PD+ compared with the iPD subjects, 22.2 versus 15.1%, respectively." (PMID 29568677, 2018). "Non‐skin cancers were diagnosed in 18 (17.5%) in the LRRK2 group and 126 (15.1%) in the iPD group." (PMID 29568677, 2018).
ulcerative colitis (7 papers, 2018 to 2026). An inflammatory bowel disease involving the mucosal surface of the large intestine and rectum. "Bioinformatics analysis revealed that Lrrk2 is a target gene of miR-369-3p, and LRRK2 expression was increased in ulcerative colitis patients compared with that in a healthy control." (PMID 41977401, 2026).
autonomic dysfunction (6 papers, 2021 to 2025). "In LRRK2 G2385R carriers, female sex showed a lower risk of autonomic dysfunction (OR = 0.294, p = 0.024, 95%CI 0.102–0.849) compared with male." (PMID 33771108, 2021). "In LRRK2 G2385R carriers, female sex showed a lower risk of autonomic dysfunction (OR = 0.294, p = 0.024)." (PMID 33771108, 2021). "This study aimed to assess the profile of autonomic dysfunction symptoms in three groups of patients with genetic PD, carrying mutations in GBA, LRRK2, and PRKN genes, compared with subjects with sporadic PD." (PMID 40904824, 2025). "In female sex, LRRK2 G2385R carriers showed lower risk in autonomic dysfunction compared with non-carrier (OR = 0.401, p = 0.040, 95%CI 0.167–0.960)." (PMID 33771108, 2021). "After adjusted by age and disease duration, we found that females with LRRK2 G2385R carriers showed lower risk in autonomic dysfunction (OR = 0.401, p = 0.040) as compared with females without LRRK2 G2385R non-carriers." (PMID 33771108, 2021). "However, in female sex, a lower risk of autonomic dysfunction was found in LRRK2 G2385R carriers compared with non-carriers." (PMID 33771108, 2021). "While the results for LRRK2 were less robust after adjustment, and data on PRKN remain inconclusive due to the small sample size, our study reinforces the importance of considering genotype in the clinical evaluation of autonomic dysfunction in PD." (PMID 40904824, 2025). "In the present study, female sex in PD with LRRK2 G2385R non-carriers had milder severity in motor symptoms and lower risk in EDS, autonomic dysfunction and SN hyperechogenicity but higher risk in mood disorders, which is in agreement with most published data." (PMID 33771108, 2021).
brain injury (6 papers, 2018 to 2023). Acute and chronic (see also brain INJURIES, CHRONIC) injuries to the brain, including the cerebral hemispheres, CEREBELLUM, and brain STEM. "The high kinase activity of LRRK2 is associated with defects in protein synthesis and degradation, apoptosis, inflammatory responses, and oxidative damage, which are also factors that trigger acute brain injury following TBI." (PMID 29545743, 2018). "This study was designed to investigate the potential role and mechanism of LRRK2 in secondary brain injury after traumatic brain injury (TBI)." (PMID 29545743, 2018). "We found that various in vitro and in vivo models of traumatic brain injury (TBI) markedly enhanced LRRK2 expression in neurons and also increased the level of hypoxia-inducible factor (HIF)-1α." (PMID 30420654, 2018). "Similarly, LRRK2 contributes to traumatic brain injury (TBI)-induced neuronal apoptosis, BBB permeability, brain edema and neurological impairment." (PMID 34848837, 2021).
essential tremor (6 papers, 2015 to 2025). A relatively common disorder characterized by a fairly specific pattern of tremors which are most prominent in the upper extremities and neck, inducing titubations of the head. "The following findings are notable: LRRK2 is associated with a prior diagnosis of essential tremor (ET)." (PMID 33935957, 2021). "In our cohort, gene-based tests reveal an association between LRRK2 and history of essential tremor." (PMID 33935957, 2021). "However, while LRRK2 p.N551K and p.R1398H variants seem to have a protective effect for PD, this protective effect could not be shown for essential tremor or AD." (PMID 33494262, 2021).
glioma (6 papers, 2016 to 2024). A benign or malignant brain and spinal cord tumor that arises from glial cells (astrocytes, oligodendrocytes, ependymal cells). "A pan-cancer analysis of LRRK2 revealed that LRRK2 increases the risk of low-grade glioma but serves as a protective factor for survival of patients with cutaneous melanoma." (PMID 39006030, 2024). "Expression levels of risk factors BRCA1, DNM1L, RCN1, HSPB1, RPN2, LRRK2 and SPP1 in high‐grade gliomas were greater than those in lower‐grade gliomas, while the protein expression levels of protective factor PDIA3 were exactly the opposite." (PMID 33611848, 2021).
Huntington disease (6 papers, 2008 to 2022). Huntington disease (HD) is a rare neurodegenerative disorder of the central nervous system characterized by unwanted choreatic movements, behavioral and psychiatric disturbances and dementia. "HC-AdV vectors have been used for modelling inflammation related to neurodegenerative diseases, by overexpression of a mutated form of leucine-rich repeat kinase 2 (LRRK2) in mice and NHPs; and for developing a chronic in vitro model of Huntington ́s disease in primary neuronal cultures." (PMID 32455640, 2020).
pancreatic cancer (6 papers, 2014 to 2024). "Adenosine cobalamin, a form of vitamin B12, effectively blocks LRRK2 and improves the response to PD-L1 immunotherapy in mice with pancreatic cancer." (PMID 38654302, 2024). "This approach, in which PD-L1 blockade is combined with LRRK2 inhibition, appears promising as a new treatment strategy for pancreatic cancer." (PMID 38654302, 2024). "To assess the functional effects of LRRK2-IN-1 in vitro we chose to focus on the AsPC-1 human pancreatic cancer and HCT116 human colon cancer cell lines, which are both well characterized for their DCLK1 expression in the literature." (PMID 24885928, 2014). "As previous studies have shown that targeting DCLK1 with kinase inhibitors resulted in significant reduction of clonogenic potential and invasive capacity in pancreatic cancer and renal cell carcinoma cell lines, we next assessed the impact of LRRK2-IN-1 induced DCLK1 inhibition on HNSCC cell lines." (PMID 34336664, 2021). "Notably, a small molecule LRRK2 inhibitor, LRRK2-IN-1, demonstrated activity in colorectal and pancreatic cancer via direct inhibition of DCLK1; the clinical utility of such therapeutic agents could also spawn further from LRRK2-overexpressed cases." (PMID 32722212, 2020).
Postural instability (6 papers, 2018 to 2024). A tendency to fall or the inability to keep oneself from falling; imbalance. "Fourth, we did not analyze the LRRK2 characterized by relatively preserved cognitive functions and a postural instability and gait disorder phenotype and GBA mutations related to higher frequencies of visual hallucinations and a worse cognitive profile." (PMID 35386951, 2022). "Some research reported more frequent subtype of postural instability/gait difficulty and motor fluctuation in patients with LRRK2 G2385R variant, but no major clinical differences except for the non-significant milder non-motor symptoms were found in PD patients with LRRK2 in most previous studies." (PMID 33771108, 2021).
psychosis (6 papers, 2014 to 2025). "For example, patients with GBA1-associated PD have shown a higher prevalence of non-motor features, such as dementia, probable REM sleep behavior disorder (RBD), and psychosis, in contrast to those with LRRK2-PD or MNPD." (PMID 40422213, 2025). "Interestingly, despite carrying risk variants in both LRRK2 and GBA1, dual mutation carriers (LRRK2-GBA1-PD) tend to exhibit a lower frequency of RBD and psychosis than patients with single GBA1 mutations, suggesting a complex and possibly modulating interaction between these genetic factors." (PMID 40422213, 2025). "Delusions or severe psychosis did not occur in any LRRK2-PD nor IPD patient." (PMID 25330404, 2014).
schizophrenia (6 papers, 2017 to 2025). A major psychotic disorder characterized by abnormalities in the perception or expression of reality. "Investigating the effects of LRRK2 inhibition on the complex and less well-understood effect of haloperidol on the positive symptoms of schizophrenia would be valuable in future studies." (PMID 40269187, 2025). "There are also agonists or activators for products of six DEGs that are down-regulated in ASD (Lrrk2), schizophrenia (Chrm4, Prkca), schizophrenia and BP (Klf2) or schizophrenia, BP and MDD (Nr4a1 and Nr4a3)." (PMID 39502833, 2024). "We transformed these proteins to their encoding gene IDs and identified the top 20 genes as the most probable schizophrenia-risk genes, including the EYA3, CNTN4, HSPA8, LRRK2, and AFP genes." (PMID 37966892, 2023). "We also explored the LRRK2 L1165P variant which is exceedingly rare and detected in a single early-onset PD case with unclear causality, as well as a LRRK2GS subject with Schizophrenia and no PD diagnosis which was reported to have no pathology (α-synuclein or tau)." (PMID 40661559, 2025).
clear cell renal cell carcinoma (5 papers, 2021 to 2026). "LRRK2 has been identified to be a candidate prognostic biomarker for clear cell renal cell carcinoma." (PMID 35247252, 2022). "The LRRK2 is also involved in the tumorigenesis and progression of clear cell renal cell carcinoma." (PMID 36590916, 2022).
corticobasal degeneration (5 papers, 2019 to 2025). "Multiple population studies have found that LRRK2 mutations are very rare in pathologically-confirmed primary tauopathies PSP or corticobasal degeneration (CBD), suggesting that LRRK2 mutations are primarily associated with PD." (PMID 31733655, 2019). "One LRRK2 carrier was diagnosed with corticobasal degeneration, all others had PD." (PMID 40672482, 2025).
leukemia (5 papers, 2020 to 2025). A malignant (clonal) hematologic disorder, involving hematopoietic stem cells and characterized by the presence of primitive or atypical myeloid or lymphoid cells in the bone marrow and the blood. "Our analysis of PPMI data indicated that among LRRK2 mutation carriers, the cancers most frequently observed were non-melanoma skin tumors and hematologic malignancies such as lymphoma, leukemia, and multiple myeloma." (PMID 41300754, 2025). "In a study comparing patients with IPD, patients with LRRK2-PD, and persons from a control group, the patients with LRRK2-PD had a 4.6-fold increased risk of leukemia compared to the IPD patients and to the control group." (PMID 33066407, 2020). "Another study showed the increased risks of leukemia among Parkinson individuals with leucine-rich repeat kinase 2 gene." (PMID 41199954, 2025).
Obesity (5 papers, 2013 to 2025). Accumulation of substantial excess body fat. "In line with this, a recent study correlates increased LRRK2 protein expression and obesity in mice." (PMID 40676250, 2025). "These biochemical assays support attenuation to the biological response in HFD‐induced obesity in LRRK2 knockout animals." (PMID 37845194, 2023). "Direct links between LRRK2 function and the development of obesity were also revealed by this analysis." (PMID 23799078, 2013). "Molecular pathway analysis of LRRK2 reveals direct links between LRRK2 and the thioredoxin system, which interacts with PRDX3, TXNIP and TXNRD1, proteins that are associated with nutrient sensing, adiposity and human obesity." (PMID 23799078, 2013). "However, given that obesity induces infiltration of immune cells such as macrophages into adipose tissue, it will be crucial to discern whether the rise in LRRK2 expression in obese adipose tissue is intrinsic to adipocytes or a consequence of immune cell infiltration." (PMID 37845194, 2023).
orthostatic hypotension (5 papers, 2020 to 2025). Sudden fall of the blood pressure of at least 20/10 mm Hg when a person stands up. "First, we show that LRRK2 p.G2019S PD has the lowest prevalence of hallucinations, RBD, hyposmia, nocturia, orthostatic hypotension, difficulties with concentration, and MCI diagnoses." (PMID 40926580, 2025). "Subgroup analysis highlighted specific issues including constipation, early satiety, and heat intolerance in both the GBA and LRRK2 groups, orthostatic hypotension in the GBA group and urinary incontinence and excessive perspiration in the LRRK2 group." (PMID 40904824, 2025).
Stroke (5 papers, 2019 to 2025). Sudden impairment of blood flow to a part of the brain due to occlusion or rupture of an artery to the brain. "To re-examine MLi-2 inhibitory values, stroke-induced mice showing significantly increased LRRK2 activity in Rose-Bengal (RB) photo-thrombosis were examined." (PMID 40629324, 2025). "Results showed co-localize high activity of LRRK2 with mitophagy-related proteins and that MLi-2 could attenuate mitochondrial apoptosis, ultimately leading to neuroprotective potential in stroke progression." (PMID 40629324, 2025). "LRRK2, CALM1, CXCR4, TLR4, CTNNB1, and CXCR2 may be implicated in AF and the hub-genes of CD19, FGF9, SOX9, GNGT1, and NOG may be associated with stroke." (PMID 30760287, 2019).